CEACAM1 (CEA cell adhesion molecule 1)
Diseases named in the same sentence as CEACAM1 in open-access papers (continued):
Sharing a sentence is not in itself a finding about the gene and the disease.
colon carcinoma (continued). "CEACAM1 on NETs plays a crucial role in the adhesion and migration of colon carcinoma cells." (PMID 39143953, 2024). "Furthermore, CEACAM1 on NETs is important for the adhesion of murine colon carcinoma cells to liver sinusoids in vivo." (PMID 39143953, 2024). "Most colon tumors exhibit a marked reduction of apoptosis and decreased CEACAM1." (PMID 36741860, 2023). "For instance, colon cancer biomarkers CEACAM1 and MUC13 could be found in MVs derived from colon cancer cells, which could assist in the diagnoses of colorectal cancers." (PMID 36045692, 2022). "In colon cancer, a dynamic regulation of CEACAM1 appears dependent on the stage of the disease, which might potentially reflect the CEACAM profile seen in pediatric versus adult IBD." (PMID 34394073, 2021). "In conclusion, the anti-CEACAM1 antibody 6G5j may be a useful probe for primary colon cancer and metastasis detection for fluorescence-guided surgery." (PMID 32064046, 2020). "Since this mAb binds to multiple antigens that are commonly present in colon tumors, namely CEACAM1, 5 and 6, it may provide improved detection of cancer margins for tumors with variable expression of CEA and other CEACAMs." (PMID 32064046, 2020). "Additionally, CEACAM1 expression was required in murine colonic tumor cells to down-modulate activity of the β-catenin-inducible promoter, which is in agreement with our findings." (PMID 27572314, 2016). "Importantly, overexpression of either CEACAM1 or CEACAM5 in CEACAM5-HLA-Ilow colonic tumor cells could prevent NK cytotoxicity against these cells." (PMID 21731662, 2011). "CEACAM1, CEACAM5 and CEACAM6 have been demonstrated to be over-expressed in certain epithelial cancers, such as colon cancer." (PMID 32064046, 2020). "Similarly, a broad reduction in cell adhesion markers including CEACAM1, CEACAM5, CEACAM6, and CEACAM7 occurs in human colon cancer cell lines after treatment with chloroquine." (PMID 39900438, 2025). "We further investigated the role of CEACAM1 in ammonia-mediated disruption of TGF-β signaling, by examining p-SMAD3 in SW480 human colon cancer cells after overexpressing either full-length CEACAM1 (CEACAM1-FL) or a C-terminal deletion mutant lacking the ITIM motif (CEACAM1-ΔC)." (PMID 40311681, 2025). "In addition, SLC7A8 was upregulated alongside two tumour suppressor genes, CEACAM1 and BMP2, in human colon cancer cells after exposure to anti-tumour agent." (PMID 32200487, 2020). "CEACAM1, CEACAM5 and CEACAM6 are co-expressed in epithelial cells of the gastro-intestinal tract and can also be over-expressed in endometrial, lung, ovarian, cervical, breast and colon cancers." (PMID 32064046, 2020). "It was found that both CEACAM1-4S and 4L overexpression could promote the invasive and metastatic ability of colon cancer cell line HT2925, 26, while the invasive and metastatic ability of hepatocellular carcinoma cell line HLF was impaired after overexpression of CEACAM1-4S and 4L27." (PMID 39513107, 2024). "In contrast to CEACAM1-4L, CEACAM1-4S failed to generate a tumor suppressor phenotype when re-expressed in r-HCC or mouse colon carcinoma cell lines." (PMID 22235309, 2012).
colorectal cancer (32 papers, 2010 to 2026). A primary or metastatic malignant neoplasm that affects the colon or rectum. "NETs-associated CEACAM1 promotes colorectal cancer cell adhesion and migration in vitro/vivo, and increases the possibility of metastasis formation in vivo." (PMID 41019086, 2025). "CEACAM1 is an immunoglobulin involved in cell-to-cell adhesion, and its overexpression is implicated in colorectal cancer." (PMID 25719429, 2015). "The loss of expression and genetic alteration of the CEACAM1 may be an early event for colorectal cancers development." (PMID 34131588, 2021). "Furthermore, somatic missense mutations in colorectal cancers have been detected in CEACAM1 and CEACAM5, the latter of which has been shown to increase proliferation by inhibiting TGFB signaling and altering the intestinal microbiome." (PMID 34447411, 2021). "Moreover, cell proliferation inhibition of human colorectal carcinoma cell line (Caco-2) is associated with G2/M cell cycle arrest and a sharp up-regulation of the tumor suppressor carcinoembryonic antigen-related cell adhesion molecule 1 (CEACAM1)." (PMID 22412883, 2012). "Overall, CEACAM1 is downregulated in colorectal cancer, upregulated in gastric cancer, and directly correlated with decreased overall survival in HCC and gastric cancer." (PMID 36741860, 2023). "Based on its downregulation in early stages of colorectal cancer (CRC) detected in some of the earlier studies CEACAM1 was initially regarded as a potential tumor suppressor." (PMID 38077351, 2023). "The TGF-β pathway plays an integral role in the suppression of early colorectal cancers, yet in advanced colorectal cancers, it plays a prominent tumor promoting role—in some ways similar to CEACAM1 function." (PMID 36741860, 2023). "Another newly identified molecule that promotes metastasis in colorectal cancer is carcinoembryonic antigen-related cell adhesion molecule 1 (CEACAM1), a cell adhesion molecule expressed on endothelial cells." (PMID 36613779, 2022). "A synergistic antitumor effect has been shown with the simultaneous blockade of TIM-3 and CEACAM1, as well as CEACAM1 and PD-L1, on murine colorectal cancer tumors." (PMID 36140182, 2022). "The expression of selected genes related to MG degradation III (AKR1B10, AKR1C2 and ADH4), glyoxalase system (GLO1 and HAGH), glucose transport (SLC2A1 and SLC5A1) and colorectal cancer-associated genes (AREG, CXCL8 and CEACAM1) were quantitated using qRT-PCR." (PMID 32561807, 2020). "On the other hand, we have reported that if the cancer cells constantly express CEACAM1 such as colorectal cancer and HCC, CEACAM1-L dominant balance promotes malignant phenotypes including invasion, metastasis and poor prognosis." (PMID 31481751, 2019). "In colorectal cancer and hepatocellular carcinoma (HCC), we have reported that CEACAM1 is associated with invasion, metastasis and poor prognosis." (PMID 31481751, 2019). "We have already reported that CEACAM1-4L promotes invasiveness of colorectal cancer and hepatocellular carcinoma, resulting in that CEACAM1-L dominant expression is associated with poor survival." (PMID 31481751, 2019). "CEACAM1 long cytoplasmic domain isoform (CEACAM1-4L) promotes colorectal cancer cell invasion and migration." (PMID 31481751, 2019). "On the other hand, CEACAM1 has been described as a driver of invasion and metastasis in colorectal cancer and hepatocellular carcinoma." (PMID 30050594, 2018). "Recently, a CEACAM1-associated decrease of STAT3 activity and CCL2 secretion was found in colorectal carcinoma, thus regulating inflammatory signalling networks and decreasing metastatic burden." (PMID 30050594, 2018). "More interestingly, mAb CC4 is able to enhance NK cytotoxicity against MHC-I-deficient colorectal cancer cells by blocking intercellular interaction between epithelial CEACAM5 and NK inhibitory receptor CEACAM1." (PMID 21731662, 2011).
colorectal cancer (continued). "As we revealed the interplay of various cell types including colonocytes and cycling cells in CEACAM1_CEACAM5 interaction in IBD or colorectal cancer patients, it might highlight targeting these cells to reverse the adverse conditions." (PMID 37414760, 2023). "CEACAM-1 is a cell-surface protein expressed by immune cells and tumor cells, and it plays a role in inhibiting T cell function and in promoting T cell exhaustion in colorectal cancer patients." (PMID 35804808, 2022). "Moreover, sensitivity and accuracy of combined APEX1 and carcinoembryonic antigen-related cell adhesion molecule 1 (CEACAM1) in the diagnosis of colorectal cancer were significantly higher than individual detection of APEX1 or CEACAM1." (PMID 31454981, 2019). "Likewise, Lewisa and Lewisb epitopes displayed on CEA and CEACAM1 from colorectal cancer cells can also be recognized by DC-SIGN." (PMID 29527514, 2018). "We showed here that mAb CC4 could markedly enhance NK cytotoxicity against colorectal cancer cells by disrupting the inhibitory interaction of tumor CEACAM5 or CEACAM1 with NK CEACAM1." (PMID 21731662, 2011). "We transfected CEACAM1- and CEACAM5-expressing plasmids into colorectal cancer HCT-15 cells, respectively, and then generated stable cell lines, designated as HCT-15/CEACAM1 and HCT-15/CEACAM5." (PMID 21731662, 2011). "Ceacam1 is a CEA-related cell adhesion molecule downregulated in several human cancer types, including prostate, breast, and colorectal cancers." (PMID 20525254, 2010). "In gastric cancer, there is a possibility that similar changes, such as colorectal cancer and HCC, may occur by expression and cytoplasmic domain isoform balance of CEACAM1." (PMID 31481751, 2019). "Above findings led to the possibility that mAb CC4 may interfere with the cell-cell contact between CEACAM1 expressed on immune cells and CEACAM5 expressed on colorectal cancer cells." (PMID 21731662, 2011). "Thus, the tumor immune evasion mechanism that up-regulation of CEACAM1 or CEACAM5 activates inhibitory CEACAM1 signaling in NK cells and then circumvents NK cytotoxicity also exists in colorectal cancer cells." (PMID 21731662, 2011). "There is one study showing the coexpression of CEACAM1 and TIM-3 molecules on CD8+ T cell in a mouse colorectal cancer model and human colorectal cancer patients, and CEACAM1 can be upregulated by IFN-γ and interleukin-27, leading to the suggestion that CEACAM1 may be a phenotype of failing T cells." (PMID 36712923, 2023). "The majority of colorectal cancer and HCC express CEACAM1 and it is rare that colorectal cancer and HCC have no expression of CEACAM1." (PMID 31481751, 2019). "In general, CEACAM1-positive cancer such as colorectal cancer and HCC is not aggressive and has predictable prognosis, whereas CEACAM1-negative cancer, such as gastric cancer, is aggressive and has unpredictable prognosis." (PMID 31481751, 2019).
Insulin resistance (31 papers, 2011 to 2026). Increased resistance towards insulin, that is, diminished effectiveness of insulin in reducing blood glucose levels. "Mice with hepatocytes-specific deletion (AlbCre+Cc1fl/fl) or inactivation (L-SACC1) of Ceacam1 provide an in vivo demonstration that hepatic inflammation and fibrosis can be associated with visceral obesity, insulin resistance, and hepatic steatosis." (PMID 39640841, 2024). "Sustained high fat intake for > 3 weeks causes a loss of CEACAM1 by > 60%, at which point, insulin clearance is impaired and hepatic insulin resistance develops preceding inflammation." (PMID 39640841, 2024). "In mice, conditional deletion of CEACAM1 in hepatocytes impairs insulin clearance to cause hyperinsulinemia-driven insulin resistance with steatohepatitis and hepatic fibrosis even when mice are fed a regular chow diet." (PMID 39640841, 2024). "This appeared to be due to TNFα-mediated induction of the anti-inflammatory CEACAM1-4L variant in M2 macrophages associated with white adipose tissue to enhance innate immunity and counter inflammation-driven insulin resistance." (PMID 35457157, 2022). "Studies in mice deficient in Ceacam1, one of the best characterized proteins involved in insulin clearance, suggest that diminished clearance promotes insulin resistance." (PMID 34206745, 2021). "Recently, it has been demonstrated that complete mutation in CEACAM1 gene (Ccl-/−) brings to impartments of insulin clearance causing hyperinsulinemia and limited insulin resistance." (PMID 32326243, 2020). "CEACAM1 is involved in promoting insulin clearance and its loss in hepatic expression has been shown to link insulin resistance to obesity and NAFLD." (PMID 31805072, 2019). "Collectively, this positions the loss of hepatic CEACAM1 expression (and its resulting hyperinsulinemia and insulin resistance) on the crossroad of the pathogenesis of NAFLD and obesity." (PMID 28184213, 2017). "Fed a regular chow diet, global null mutation of Ceacam1 manifest hyperinsulinemia, insulin resistance, obesity, and steatohepatitis." (PMID 28184213, 2017). "Further emphasizing the metabolic role of hepatic CEACAM1, liver-specific overexpression of CEACAM1 curbs the metabolic abnormalities caused by high-fat diet and prevents insulin resistance and hepatosteatosis." (PMID 28184213, 2017). "Together, this emphasizes that loss of hepatic CEACAM1 links NAFLD to insulin resistance and obesity." (PMID 28184213, 2017). "Null deletion or liver-specific inactivation of Ceacam1 in mice causes a defect in insulin clearance, insulin resistance, steatohepatitis, and visceral obesity." (PMID 28396653, 2017). "We have recently shown that high-fat (HF) intake causes insulin resistance in part by reducing CEACAM1 mRNA and protein levels in liver." (PMID 26284027, 2015). "The carcinoembryonic antigen-related cell adhesion molecule 1 (CEACAM1) is an important candidate for causing insulin resistance." (PMID 21569294, 2011). "Inactivation of CEACAM1 impairs insulin clearance and causes hyperinsulinemia, insulin resistance, dyslipidemia and visceral adiposity in transgenic mice." (PMID 21569294, 2011). "Moreover, liver‐specific CEACAM‐1 deletion in mice causes insulin resistance, HI, and increased hepatic lipid synthesis and accumulation." (PMID 40476757, 2025). "Thus, loss of CEACAM1 provides an in vivo demonstration that hepatic inflammation and fibrosis can occur independently of insulin resistance and hepatic steatosis." (PMID 39640841, 2024). "As previously shown, the loss of CEACAM1 by >50% lowers hepatic insulin clearance to contribute to chronic hyperinsulinemia and its downregulatory effect on insulin receptor levels to sustain hepatic insulin resistance." (PMID 36009446, 2022). "The reduction of hepatic CEACAM1 caused insulin resistance and obesity in mice and other species." (PMID 32899471, 2020).
Insulin resistance (continued). "Together with visceral obesity, sustained hyperinsulinemia reduces glucose transporter 4-mediated glucose transport to cause insulin resistance in adipose tissue, as supported by hyperinsulinemic-euglycemic clamp analysis in Ceacam1 mutants and in the diet-induced model." (PMID 28184213, 2017). "As summarized in this review, our laboratory has demonstrated in the last couple of decades that loss in hepatic CEACAM1 expression and its defective phosphorylation impair insulin clearance and subsequently, play a pivotal role in insulin resistance, fatty liver disease, and obesity." (PMID 28184213, 2017). "Of note, while our studies show that reduction of hepatic CEACAM1 causes insulin resistance, hepatosteatosis, and visceral obesity, they also show that diet-induced visceral obesity represses hepatic CEACAM1 to cause fat accumulation in liver and insulin resistance." (PMID 28184213, 2017). "Mice with liver-specific inactivation (L-SACC1) or with global null mutation of Ceacam1 (Cc1−/−) exhibit impairment in insulin clearance leading to chronic hyperinsulinemia and systemic insulin resistance (owing to downregulation of insulin receptor expression)." (PMID 28184213, 2017). "The recent data from articles suggests that carcinoembryonic antigen-related cell adhesion molecule 1 (CEACAM1) is an important candidate molecules that may cause insulin resistance." (PMID 21569294, 2011). "Thus, there is a strong association between severe visceral obesity, insulin resistance and a reduced hepatic CEACAM1 level." (PMID 21569294, 2011). "Mice fed a high-fat diet for three weeks exhibited significantly reduced hepatic CEACAM1 expression by more than 50 percent, accompanied by observations of hyperinsulinemia, insulin resistance, and elevated liver triacylglycerol levels." (PMID 40985048, 2025). "For these reasons, we will expand our discussion on CEACAM1 in liver pathology of insulin resistance and MASLD, as it is an emerging significant player in disease progression." (PMID 40985048, 2025). "In this study, exenatide induces Ceacam1 expression and improves insulin clearance, insulin resistance, and liver fat accumulation in high-fat diet-fed mice." (PMID 40699685, 2025). "In people with insulin resistance, hepatic CEACAM‐1 expression is reduced, and the amount of lipid accumulation in the liver is negatively and linearly correlated with CEACAM‐1 levels." (PMID 40476757, 2025). "Hepatic CEACAM1 levels were significantly reduced in 29% of South Korean obese subjects with insulin resistance and hepatic steatosis independently of diabetes." (PMID 39640841, 2024). "Recapitulating the human disease, mice with global deletion of Ceacam1 (Cc1−/−) exhibited hyperinsulinemia-driven insulin resistance, steatohepatitis and hepatic fibrosis even when fed a regular chow diet." (PMID 39640841, 2024). "Reversal of the metabolic phenotype upon liver-specific reconstitution of CEACAM1 further demonstrates the primary role of hepatic insulin clearance in the pathogenesis of insulin resistance." (PMID 36009446, 2022). "In contrast, hepatocyte-specific Ceacam1 deletion caused overt atheroma plaque formation and NASH in the presence of insulin resistance." (PMID 35457157, 2022). "Further buttressing the primary role of hepatic insulin clearance in insulin resistance, global Ceacam1 null mice manifest reduction in insulin clearance at 2 months of age, followed by systemic insulin resistance at 6–7 months of age and hepatic steatosis." (PMID 36009446, 2022). "The rise in plasma TNFα may have served to preferentially induce the expression of the Ceacam1-4L variant through activating NF-κB in the anti-inflammatory M2 macrophages of VECadherin+Cc1fl/fl to enhance innate immunity and limit systemic inflammation that would otherwise drive insulin resistance." (PMID 34440862, 2021).